NLRP3 (NLR family pyrin domain containing 3)
Diseases named in the same sentence as NLRP3 in open-access papers (continued):
Sharing a sentence is not in itself a finding about the gene and the disease.
gout (continued). "Thus, we aimed to investigate the anti-inflammatory effect of deZP, a drug used in pharmacopuncture, on NLRP3 inflammasome-derived gouty arthritis via its effect on IL-1β regulation." (PMID 39861092, 2024). "Although the relationship between the Shigella T3SS and gout is unclear, it may be related to the induction of NLRP3 inflammasome signaling and increased inflammation." (PMID 39544522, 2024). "NLRP3 inflammasome is an inflammatory sensor of metabolic disorders that mediates the development of gout, and inhibiting the NLRP3 inflammasome might be a promising therapeutic strategy for the prevention and management of gout." (PMID 38708084, 2024). "These decreases in arthritic severity and inflammatory cell infiltration were almost completely reversed by the intra-articular injection of recombinant IL-1β into the affected joints, demonstrating the decisive role of the myeloid NCOA6–IL-1β axis in NLRP3-dependent gouty arthritis." (PMID 38195836, 2024). "Furthermore, MCC950 treatment significantly ameliorated mechanical allodynia of gout model mice, demonstrating the critical contribution of NLRP3 inflammasome to mechanical pain of gout arthritis model mice." (PMID 37464384, 2023). "In gout flares, the initiation of NLRP3 inflammasome was considered a key step." (PMID 37637422, 2023). "SLC3037, a NLRP3 inhibitor blocking NEK7 binding to NLRP3, could be a novel agent against diseases associated with NLRP3 inflammasome activation such as gout, cardiovascular diseases, metabolic syndrome or neurodegenerative diseases." (PMID 38371945, 2023). "In addition to MSU, activation of the NLRP3 inflammasome requires a second triggering factor to induce gout flares." (PMID 36675455, 2023). "In conclusion, the NLRP3 inflammasome is expected to be a future therapeutic target for gout." (PMID 37370025, 2023). "In addition, a ketogenic diet (KD) can inhibit NLRP3 inflammasome activation by increasing the level of beta-hydroxybutyrate in neutrophils, thereby blocking IL-1β production and alleviating gout." (PMID 37370025, 2023). "We thus hypothesized that USP16 might contribute to gouty arthritis via Drp1-dependent mitochondrial fission and NLRP3 inflammasome activation." (PMID 37488647, 2023). "In rats with MSU-induced gouty arthritis, the nanoformulation inhibited the NLRP3 and NF-κB pathway, reduced the expression of pro-inflammatory cytokines in the inflamed rat joints, and ameliorated paw swelling and bone destruction more significantly than 10 alone." (PMID 38256888, 2023). "Since NEK7 is critical for NLRP3 inflammasome activation, NEK7 inhibitors could be employed as therapeutic agents against gout, a representative disease caused by NLRP3 inflammasome." (PMID 38371945, 2023). "NLRP3 inflammasome produces IL-1β in gout, composed of NLRP3, ASC, and pro-caspase-1." (PMID 37881185, 2023). "In patients with gout, the deposition and phagocytosis of monosodium urate crystals in tissues activate the NLRP3 inflammasome, leading to the production of critical cytokines such as IL-1β, IL-6, and tumor necrosis factor (TNF)-α, which are implicated in the occurrence of migraines." (PMID 38202145, 2023). "The NLRP3-mediated pyroptosis may be involved in the crosstalk between MSU-activated gout and the inflammatory cascade." (PMID 37954594, 2023). "After the involvement of the NLRP3 inflammasome in gout attacks was demonstrated, it was thought that only MSUc were responsible for the formation and activation of the NLRP3-ASC-caspase 1 protein complex, which performs proteolysis of pro-IL-1β to active IL-1β." (PMID 37996809, 2023). "The NLRP3 inflammasome in gout is activated by uric acid crystals, which lead to a disruption in the lysosomal membrane and a release of cathepsin B, increasing the formation of the NLRP3 inflammasome." (PMID 36982177, 2023). "Erianin alleviates gout by directly interacting with NLRP3 to inhibit NLRP3 assembly." (PMID 37125240, 2023).
gout (continued). "There are several in vitro and in vivo studies demonstrating the role of NLRP3 in gout." (PMID 37598797, 2023). "In addition, sulforaphane alleviated MSU‐induced arthritis symptoms and inflammatory cell infiltration in gout mice by directly inhibiting NLRP3 inflammasome activation." (PMID 37125240, 2023). "Given the well-documented role of NLRP3 in driving gout pathogenesis, a plethora of studies focused on identifying natural products, dietary elements, and novel compounds that can be used to target NLRP3 inflammasomes in gout, as well as elucidating their mechanism of action." (PMID 37598797, 2023). "Uric-acid crystals can activate the NLRP3 inflammasome in gout." (PMID 36768404, 2023). "Therefore, screening for novel pyroptosis inhibitors for treating gout should pay attention to upstream factors such as NLRP3." (PMID 37250902, 2023). "The results of their study revealed the involvement of the P2Y14R/cAMP/NLRP3 signaling pathway in acute gouty arthritis, indicating that intracellular cAMP has a distinct function in facilitating communication between P2Y14R activation and the inflammatory process during GA flares." (PMID 37954594, 2023). "Quercetin has been reported to show an anti-inflammatory effect in gouty arthritis caused by MSU, showing inhibition of IL-1β release at a concentration of 30 μM, with reports suggesting that this effect is related to inhibition of the NLRP3 inflammasome." (PMID 36234744, 2022). "A study revealed that GA has anti-inflammatory activity in gouty arthritis due to NLRP3 inhibition." (PMID 36234744, 2022). "Similar to anti-gout agent colchicine, EC could also significantly suppress protein the overexpression of NLRP3 inflammasome and the NF-κB pathway in ankle joint tissues, as well as the protein expression of p-p65 in the nucleus." (PMID 35462936, 2022). "Similarly, NLRP3 inflammasome also plays crucial role in promoting the development of rheumatoid arthritis (RA) and gout." (PMID 35774778, 2022). "MSU is an NLRP3 inflammasome activation factor for the pathogenesis of gout." (PMID 35400961, 2022). "The mRNA expression of NIMA-related kinase 7 (NEK7) and NLRP3 is upregulated in gout patients." (PMID 35464445, 2022). "Therefore, studies on the link between pyroptosis and gout should focus on upstream mechanisms, such as the NLRP3 inflammasome." (PMID 35464445, 2022). "MSU crystals can motivate the activation of NLRP3 inflammasome, which triggers the gout flare." (PMID 36299604, 2022). "A similar observation was made upon NLRP3 inhibition in an in vivo gout model." (PMID 36225929, 2022). "NLRP3 inflammasome activation is a central process in initiating gout flares." (PMID 36052144, 2022). "Moreover, the NLRP3 inflammasome activation induced by MSU crystals plays a vital role in gout development." (PMID 35047046, 2022). "On the other side, even though macrophages and neutrophils were considered to be the principal immune cells and the NLRP3 inflammasome was the major pathway involved in gout inflammation, recent studies emphasized an emerging role of T cell subsets in the pathogenesis of gout." (PMID 35197978, 2022). "At the same time, this study clarified the critical role and correlation of uric acid metabolism targets and NLRP3 inflammasome in the progression of gout, which can provide a reference for clinical drug development and efficacy evaluation of gout prevention and treatment." (PMID 36569836, 2022). "In addition, In vitro and in vivo studies have demonstrated the activation and upregulation of NLRP3 in painful conditions including gout and rheumatoid arthritis; however, inhibition of NLRP3 expression can mediate analgesia." (PMID 35775127, 2022). "Thus, it is important to identify these pathways and understand their interactions with the NLRP3 inflammasome and IL-1β production during the development and resolution phases of gout." (PMID 35370689, 2022). "Activation of the NLRP3 inflammasome in MSU-induced gout involves two signals." (PMID 35400961, 2022).
gout (continued). "Accumulating evidence indicates that the NLRP3 inflammasome plays a significant role in the innate and adaptive immune systems and the development of various arthritic illnesses, such as rheumatoid arthritis, ankylosing spondylitis, and gout." (PMID 36387275, 2022). "The activation of NLRP3 inflammasome accompanies the onset of gouty arthritis in quail." (PMID 36569836, 2022). "In conclusion, these findings suggested that compound 2 may effectively improve NLRP3 inflammasome-mediated gout via PI3K-AKT-mTOR-dependent autophagy and could be further investigated as a potential agent against gout." (PMID 35047046, 2022). "Although it is widely accepted that gout is an inflammatory disease characterized by urate crystal-induced NLRP3 inflammasome activation with up-regulated caspase-1 protease and IL-1β in macrophages, recent evidence has highlighted that serum IL-17 levels are significantly elevated in gout patients." (PMID 35197978, 2022). "It is well-known that NLRP3 inflammasome is important inflammatory triggers during gout flare." (PMID 36051474, 2022). "The results indicated that compound 2 may effectively improve NLRP3 inflammasome-mediated gout via PI3K-AKT-mTOR-dependent autophagy." (PMID 35047046, 2022). "Considering that the NF-κB and NLRP3 inflammasome pathways are related to the development of many inflammatory diseases, neoastilbin may have potential clinical application value in gout, autoinflammatory syndrome or other NLRP3-driven diseases." (PMID 35684415, 2022). "Therefore, the inhibition of NLRP3 inflammasome-mediated IL-1β production process is a new and beneficial strategy for the treatment of gout." (PMID 35047046, 2022). "The relationship between the uric acid metabolism target and the NLRP3 inflammasome may be the critical immune response between hyperuricemia and gouty arthritis." (PMID 36569836, 2022). "IRDs related to the NLRP3 inflammasome include both monogenic diseases, such as cryopyrin-associated periodic syndrome (CAPS), and polygenic diseases, such as Crohn’s disease (CD) and gout." (PMID 36142364, 2022). "Therefore, the inhibition on NLRP3 inflammasome and the release of pro-inflammatory cytokines are crucial targets in the treatment of acute gouty arthritis." (PMID 34586567, 2022). "NLRP3 inflammasome dysregulation enhances the pathogenesis of gout." (PMID 35400961, 2022). "In this study, we found that LXA4 could inhibit NLRP3 inflammasome in gouty arthritis model, which is consistent with other studies." (PMID 36569930, 2022). "Such an overview suggests that the use of natural products acting at various stages of NLRP3 signaling may be a suitable pharmacological approach for the management of acute and chronic gout." (PMID 35370689, 2022). "However, there is currently a lack of more in-depth research on the effect of dapansutrile on protein targets such as NLRP3 in gouty arthritis." (PMID 36105284, 2022). "By observing the whole pathological process of gout, we found that the relationship between the uric acid metabolism target XOD and the NLRP3 inflammasome may be the critical immune response between hyperuricemia and gout." (PMID 36569836, 2022). "In conclusion, we hypothesize that P. igniarius may down-regulate MSU crystal-induced gout-related inflammatory factor expression in HUVECs through mediating the TLR4/NF-κB/NLRP3 signaling pathway." (PMID 36339594, 2022). "This could be evidence of a new pharmacological strategy of anti-NLRP3 inflammasome activators in the prevention and treatment of gout onset." (PMID 35370689, 2022). "Inhibits NLRP3 activation in experimental models of gout by regulating ASC oligomerization." (PMID 35464445, 2022). "Therefore, further research on natural products and their regulation of NLRP3 inflammasome assembly in a wide range of gout is needed to elucidate various pharmacological mechanisms and develop effective gout therapeutics." (PMID 35370689, 2022).
gout (continued). "Similarly, mitochondrial stress has been shown to induce NLRP3 inflammasome activation leading to many chronic diseases, including gout." (PMID 36447664, 2022). "Collectively, our results provide a potent P2X7R allosteric inhibitor that facilitates the remission of MSU crystal-induced gout inflammation by inhibiting NLRP3 inflammasome activation, suggesting that allosteric inhibition of P2X7R represents a new direction in gout treatment." (PMID 36052144, 2022). "The pathogenesis of MSU-induced gout involving these components may be initiated and amplified by IL-1β, a key regulator of gout maturated by the NLRP3 inflammasome." (PMID 35400961, 2022). "Owing to increased intracellular protoporphyrin IX/DRP-1-mediated mitochondrial fission, abnormal protein function results in aggregate formation, leading to excessive reactive oxygen species activation of the NLRP3 inflammasome, which plays a role in the development of gout." (PMID 35813212, 2022). "Although corilagin treats gouty arthritis by obstructing the NLRP3 inflammasome, the in vivo function of corilagin in mediating the ROS/TXNIP/NLRP3 pathway remains unclear." (PMID 36299604, 2022). "Furthermore, LXA4 also alleviated the severity of NLRP3-driven inflammation in the MSU-crystal-induced gouty arthritis mouse model." (PMID 36569930, 2022). "Kv1.5 may have therapeutic value for diseases related to gout-induced activation of the NLRP3 inflammsome, including AF." (PMID 35368226, 2022). "First, we investigated whether Z1456467176 affected P2X7R-induced NLRP3 inflammasome activation in gout." (PMID 36052144, 2022). "Taken together, our study revealed the effect of CPT on the treatment of gout, and compound 2 may effectively improve NLRP3 inflammasome-mediated gout via PI3K-AKT-mTOR-dependent autophagy." (PMID 35047046, 2022). "HOTAIR knockdown alleviates gouty arthritis through miR-20b upregulation and NLRP3 downregulation." (PMID 35626352, 2022). "To further investigate whether the mechanism of GPS to treat acute gouty arthritis is related to NLRP3 inflammasome, we first performed western blot to analyze the activation of NLRP3 inflammasome in vivo study." (PMID 34586567, 2022). "Therefore, although the role of the NLRP3/IL-1β inflammatory signaling pathway in gout arthritis has been identified, its role in the overall progression of gout disease is unclear." (PMID 36569836, 2022). "Furthermore, βOHB improved NLRP3 inflammasome-mediated inflammatory diseases, such as Muckle-Wells syndrome, spinal cord injury, and gout flares, and reduced caspase-1 activation and IL-1β secretion." (PMID 35585627, 2022). "As recently reviewed by Spel, several SNPs in the genes encoding NLRP3, NLRP1, IL-1β, and IL-18, which lead to increased expression levels, were connected to the development of rheumatoid arthritis, gout, ankylosing spondylitis, and juvenile idiopathic arthritis." (PMID 35629398, 2022). "Interestingly, LXA4 also significantly inhibited the expression of NLRP3, cleaved caspase-1, and matured IL-1β in the joint of gouty arthritis rats." (PMID 36569930, 2022). "The NLRP3 (NOD-, LRR-, and pyrin domain containing 3) inflammasome is one of the most interesting targets implicated in various inflammatory diseases (e.g., Alzheimer’s disease, atherosclerosis, and gout)." (PMID 36234744, 2022). "This review examines the function of the NLRP3 inflammasome in the development of autoimmune disorders, such as RA, AS, and gout, based on previous studies and highlights current research on the involvement of inflammasomes in inflammatory and rheumatic autoimmune disorders." (PMID 36387275, 2022). "Studies regarding natural extracts targeting NLRP3 inflammasome in gout." (PMID 35370689, 2022). "Therefore, we decided to search for a small-molecule inhibitor of the NLRP3 inflammasome for the prevention of gout inflammation." (PMID 33670601, 2021).
gout (continued). "The NLRP3 inflammasome has become an attractive therapeutic target because growing evidence has shown that its inappropriate activation is involved in the pathogenesis of many complex diseases, such as Alzheimer’s disease, type 2 diabetes, and gout." (PMID 33535473, 2021). "Hence, oridonin produces therapeutic actions on peritonitis, gouty arthritis, and type 2 diabetes in an NLRP3 inflammasome-dependent way." (PMID 34443594, 2021). "However, there is no report that miR-223 participates in the regulation of acute gout inflammation by affecting NLRP3." (PMID 33935726, 2021). "Considering that in the gout model the NLRP3 inflammasome leads to the production of IL-1β and that neutrophils represent the main source of this cytokine, our findings indicate that the regulatory effect of Ac2-26 on NLRP3 activation could be via Fpr." (PMID 33440601, 2021). "To investigate the mechanism by which loganin suppresses NLRP3 inflammasome activation, we examined whether loganin affected de novo synthesis of mtDNA in acute gout induced by MSU crystals deposition." (PMID 33670601, 2021). "The ethanolic extract of Polygonum cuspidatum can prevent and treat acute gouty arthritis in mice, and its mechanism may be related to the regulation of the expression of the NLRP3/ASC/caspase-1 axis in the gene and protein level." (PMID 34721646, 2021). "In addition to directly activating the NLRP3 inflammasome, MSU was found to stimulate the expression of P2X7 receptors and P2X4 receptors, secreting IL-1β and causing gout flares." (PMID 34925366, 2021). "Furthermore, in a mouse gout model by intraarticular MSU injection, mice deficient in NLRP3, caspase-1, or ASC showed much reduced pain response as well as reduced neutrophil infiltration and IL-1β in ankle joints." (PMID 33785039, 2021). "NLRP3 Inflammasome is an intracellular multiprotein complex, which is activated by danger signals and has recently been shown to be a promising target in inflammation models of pain and gouty arthritis." (PMID 34832855, 2021). "As a member of the family of the nucleotide-binding oligomerization domain-like receptors (NLRs), cytokine NALP3, also known as nod-like receptor protein 3 (NLRP3), is encoded by gene NLRP3, playing an important role in the MSU-mediated gout inflammation and immune regulation." (PMID 34359507, 2021). "Given the critical function of NLRP3 activation and induction of IL-1β in the pathogenesis of diseases such as gout, these mechanisms of action suggest that LF could have utility in other diseases as well." (PMID 34583676, 2021). "It appears that the therapeutic targeting of the NLRP3 inflammasome may be of benefit to patients with gouty arthritis; however, the effects of cardamonin on the NLRP3 inflammasome in activated macrophages remain poorly understood." (PMID 34577821, 2021). "Following tissue necrosis caused by MSU deposition, local ATP arising from the cellular release is increased, which can activate the P2X7 receptor leading to intra-and extracellular ion flow, activation of the NLRP3 inflammasome, and secretion of IL-1β, ultimately triggering a gout flare." (PMID 34925366, 2021). "Thus, it has been proposed that TLR inhibitors and NLRP3 inhibitors exert potential therapeutic effects on metabolic diseases such as gout and NAFLD." (PMID 34832960, 2021). "Uric acid crystals can activate the NLRP3 inflammasome and trigger IL-1β secretion, suggesting that inflammasome activation and IL-1β secretion are the driving factors behind the occurrence of gout." (PMID 33677475, 2021). "Furthermore, oral administration of loganin suppressed MSU crystals-induced gout inflammation in a mouse foot gout model, which was accompanied by the inhibition of the NLRP3 inflammasome." (PMID 33670601, 2021). "Next, we investigated whether loganin could prevent gout inflammation induced by NLRP3 inflammasome activation in a mouse foot gout model." (PMID 33670601, 2021).